CD4 (CD4 molecule)
Diseases named in the same sentence as CD4 in open-access papers (continued):
Sharing a sentence is not in itself a finding about the gene and the disease.
cervical tumor (14 papers, 2002 to 2026). "Moreover, analysis of immune cells from cervical tumor brush samples by flow cytometry revealed an association between high microbial diversity, increased tumor infiltration of CD4+ lymphocytes and the activation of CD4 cells over the course of radiation therapy." (PMID 33619320, 2021). "PRGN-2009 treatment reduced tumor volume and increased CD8+ and CD4+ T cells in the tumor microenvironment of humanized mice bearing the human cervical tumor SiHa." (PMID 33651712, 2021). "In another study, CD4+ T cells of patients with low-grade lesions developed a Th1 response, while patients with cervical tumor had a Th2 response elicited." (PMID 24455729, 2013). "These antitumor effects resulted from the induction of tumor-specific CD8+ T cells and CD4+ T cells that recognized cervical tumor antigens." (PMID 21649881, 2011). "Finally, cervical tumours tend to up-regulate class II HLA molecules (HLA-DR, -DP, and -DQ) that can present peptides to CD4+ T helper cells to initiate cell-mediated immune responses." (PMID 40639721, 2025). "Interestingly, in the same year there was new evidence that patients with abundant microbial diversity had increased activation of CD4+ lymphocytes infiltrating cervical tumors as well as CD4 cell subpopulation expressing ki67 and CD69+ during radiotherapy." (PMID 36798129, 2023). "Here, for the first time, we studied the modulating effect of NACT on the numbers and phenotypes of tumor-infiltrating CD4+ and CD8+ T cells in primary cervical tumors." (PMID 31616965, 2019). "The conjugated SLPs were efficiently processed by APCs, since HPV16-specific CD4+ and CD8+ T-cell clones isolated from HPV16+ cervical tumors proliferated in response to both conjugates." (PMID 27564262, 2016). "CD3, CD4, CD8, CD25, Mast Cell Tryptase monoclonal antibodies were used to characterise stroma inflammatory cells in nine cervical tumours." (PMID 12402155, 2002).
eczema (14 papers, 2007 to 2025). "It was reported that genetics plays an important role in predisposing eczema to AR, and particulate matter 2.5 (PM2.5) exposure can increase DNA methylation of IFN-γ gene promoter in CD4 + T cells." (PMID 35059372, 2021). "Compared with non-lesioned skin, among infiltrating cells in the skin lesions of lichenified eczema, the numbers of IL-13-expressing T cells, IL-4-expressing T cells (CD4+ cells), INF-γ-expressing T cells (CD4+ cells and CD8+ cells), and DCs are significantly increased." (PMID 35743125, 2022).
endotoxemia (14 papers, 2012 to 2025). "Fluctuations in naturally occurring endotoxemia in the referenced HIV-negative cohort were also associated with altered CD4+ T cell proliferation profiles and altered monocyte function." (PMID 31449552, 2019). "Thus, animals subjected to LPS-induced endotoxemia or CLP suffered a higher fractional loss of CD4+ T-cells whereas CpG or PCI treated animals suffered a proportionally higher, albeit moderate, loss of CD8+ lymphocytes." (PMID 25541945, 2014). "One study that investigated this in a mixed cohort of CVIDid and CVIDio patients reported functional exhaustion of CD4 T cells, which correlated with serum endotoxemia." (PMID 33190167, 2021). "Intravenous immunoglobulin (IVIg) treatment significantly reduces endotoxemia and PD-1+ expression on CD4+ T cells, restoring bacteria-specific CD4+ T cell cytokine production and proliferation and reducing CD8+ T cell activation." (PMID 27188997, 2016). "We observed significantly fewer CD4+CD8+ double‐positive (DP) thymocytes in the thymus of the Panx1−/‐ mice than in the WT mice after LPS stimulation, suggesting that Panx1 deficiency leads to more serious thymic involution in a mouse model of endotoxemia." (PMID 35593197, 2022). "In these studies, HIV-negative individuals with detectable but subclinical levels of endotoxemia exhibited significantly elevated levels of proinflammatory cytokines such as TNFa, IP-10, and MCP-1, as well as significantly lower CD4/CD8 T cell ratios." (PMID 31449552, 2019). "In the second cohort of CD4-depleted RMs, some of these animals were treated with DSS, which induces a low-grade endotoxemia and recapitulates aspects of pathologic SIV/HIV-1 infection." (PMID 30262807, 2018). "In our model of endotoxemia, application of homogenized AFS cells significantly increased the population of CD4+CD25+Foxp3+ regulatory T cells 24 h after endotoxemic challenge, whereas vital AFS cells only tended to show these effects." (PMID 22539976, 2012). "Remarkably, CD4+-IF1-KO mice showed no differential response to LPS-induced endotoxemia when compared to control mice." (PMID 38799559, 2024). "Studies have shown that FOS stimulated the production of CD4 and CD8 cells, which indicates that it could act as an immunostimulatory agent in endotoxemia and, therefore improve immunocompetence." (PMID 33276421, 2020). "Other previously reported immune phenotypes in MSM, such as increased frequencies of gut mucosal Th17 cells and IFN-γ+ TNF-α+ CD8+ T cells, increased endotoxemia, and lower blood CD4/CD8 ratios were either not observed or not measured in our cohort." (PMID 30947289, 2019). "On the other hand, endotoxemia evoked the alteration of the gut microbiota without the effects on inflammatory cytokines and CD4+ T cells differentiation in MNLs." (PMID 26207186, 2015).
falciparum malaria (14 papers, 2009 to 2025). "Decline in the CD4+ T cell count has also been reported to be accelerated by clinically apparent bouts of Plasmodium falciparum malaria." (PMID 26173396, 2015). "In both P. yoeliiyoelii 17XNL infection and in falciparum malaria, IL-2 is necessary for the expansion of CD25Foxp3 CD4+ T cells (T regulatory cells, or Tregs) and for activating natural killer (NK) cells, which function in the lysis of infected erythrocytes (79, –, 81)." (PMID 32958528, 2020). "In naturally infected adults with acute malaria, a prominent population of type 1 regulatory T cells arises that can be defined by high co‐expression of CD4 and CD38 (CD4hiCD38hi) and that correlates with disease severity in patients with falciparum malaria." (PMID 33282291, 2020). "Several other studies also demonstrate that falciparum malaria is more severe in HIV co-infected patients, in particular in those with decreased CD4 T-cell counts." (PMID 30563486, 2018). "To determine whether this balance is maintained by classical regulatory T cells (CD4+ FOXP3+ CD127−/low; Tregs) we compared cellular responses between Gambian children (n = 124) with severe Plasmodium falciparum malaria or uncomplicated malaria infections." (PMID 19343213, 2009). "This suggests that suppression by regulatory CD4+ T cells, known to be increased in falciparum malaria, did not account for the failure to respond to HGXPRT." (PMID 19500406, 2009).
Flavivirus Infections (14 papers, 2015 to 2024). Infections with viruses of the genus FLAVIVIRUS, family FLAVIVIRIDAE. "The role of CD4+ T cells in against flavivirus infection is also important." (PMID 36444358, 2022). "The role of CD4+T cells in flavivirus infection has been extensively documented." (PMID 32463814, 2020). "It is probable that flavivirus cross-reactive CD4 TEMRA cells are also present in individuals exposed to varied flavivirus infections or vaccines but their frequency may be very low." (PMID 32174923, 2020). "The contribution of CD4+ T cells to protect against flavivirus infection is virus-specific and may depend on the experimental system used." (PMID 27035715, 2016). "We focused on CD4 T cells directed against epitopes within the virus structural proteins, because these can mediate help to B cells by direct cell-cell interactions and are therefore essential for the production of neutralizing antibodies, the major protective correlate in flavivirus infections." (PMID 32038660, 2020). "Several studies have been carried out to identify immunodominant epitopes recognized by CD4+ and CD8+ T cells during flavivirus infections, particularly in DENV infection." (PMID 36131132, 2022). "It is well known that both CD8+ and CD4+ T cells play a major role in protection against DENV and other flavivirus infections in different experimental models." (PMID 35047876, 2020). "Our study substantiates such structural influences by demonstrating conserved epitope dominance patterns in the CD4 T cell responses after ZIKV and other flavivirus infections or vaccinations." (PMID 29899743, 2018). "During heterologous DENV infections, CD4 effector memory T cells that have a TEMRA phenotype, which is cytotoxic in nature, have also been identified and these may be present and recalled, in addition to cross-reactive Tfh cells, during heterologous flavivirus infection." (PMID 32174923, 2020).
genital warts (14 papers, 2005 to 2023). "Clearance of HPV infection is mediated by a cell-mediated immune response, and the cellular response against genital warts includes an antigen specific CD4+ Th1 response." (PMID 30616634, 2019). "In an initial study, systemic interferon therapy induced genital wart clearance, decreased viral load and increased CD4+ T cell count in immunocompromised HIV patients with recalcitrant anogenital warts." (PMID 26239450, 2015). "Tregs are found in both tissues, but in significantly different proportions : 6% of CD4+ T cells in genital warts, and as many as 25% of CD4+ T cells in laryngeal papillomas." (PMID 26023354, 2015). "The involvement of T helper 1 (Th1) cells in host defense against HPV was evidenced in this study by the overexpression of CD4, along with overexpression of IFNG, IL12B, and IL8 in genital warts." (PMID 37053156, 2023). "It should be noted that Tregs comprise only a subset of the CD4+ T cells in HPV 6 and 11 induced lesions, being approximately 6% in genital warts and 25% in respiratory papillomas." (PMID 26023354, 2015). "A history of multiple sexual partners, a history of genital warts, a history STI and a low baseline CD4 T lymphocyte were significant predictors for CIN." (PMID 24228805, 2013). "A history of multiple sexual partners, a history of genital warts, a history STI and a baseline CD4 T lymphocyte of less than 200cells/mm3 are significant predictors for CIN." (PMID 24228805, 2013). "Genital warts occur much more frequently among HIV-1 infected women in Africa, particularly among those with low CD4+ counts." (PMID 21251265, 2011). "Other limitations of our study include small sample size, the small number of incident genital warts despite the relatively large follow-up person time and the absence of HIV parameters such as viral load and CD4+ count." (PMID 30616634, 2019).
hookworm infection (14 papers, 2007 to 2024). "While these infections were generally light intensity infections, we report a clinically and statistically significant association between hookworm infection and decreased CD4+ T helper cells/mcL at study enrollment." (PMID 28542260, 2017). "The inverse association between HIV and hookworm infection, and between CD4 count and hookworm infection among HIV-positive women, is consistent with our own previous results and several other reports (." (PMID 19564904, 2009). "Participants with hookworm infection at baseline had, on average, 58 fewer CD4+ cells/mcL (95%CI: -117, 1) relative to their uninfected peers at 12-months of follow-up." (PMID 28542260, 2017). "This relationship became more pronounced when adjusting for participant age, sex, and time on ART; participants with hookworm infection had 94 fewer CD4+ cells/mcL on average (95%CI -133, -55, p = <0.001) than those without hookworm." (PMID 28542260, 2017). "Participants with hookworm infection demonstrated consistently lower concentrations of CD4+ cells/mcL when compared to hookworm-uninfected peers." (PMID 28542260, 2017). "Participants with hookworm infection had lower average CD4+ cell counts (-94 cells/mcL, 95%CI: -141, -48 cells/mcL; p<0.001) after adjustment for sex, CD4+ nadir at clinic entry, and time on ART." (PMID 28542260, 2017). "This relationship was maintained over study follow-up, where participants with hookworm infection had diminished CD4+ immune status over time, relative to their peers who were not infected with hookworm." (PMID 28542260, 2017). "We assessed the relationship between hookworm infection and CD4+ T helper cell concentrations at study enrollment." (PMID 28542260, 2017). "Trichuris and Ascaris infections were linked to increased frequencies of “activated” CD4 and/or CD8 T cells (p<0.05), whereas Hookworm infection was associated with a trend towards decreased HLA-DR+ CD8 T cell frequencies (p = 0.222)." (PMID 24675895, 2014). "Because MT is associated with decreased CD4+ T cell counts in HIV infection, we sought to determine the relationship between hookworm infection and/or MT with the numbers of CD4+ and CD8+ T cells, NK cells, and B cells." (PMID 23056659, 2012). "We show that this accumulation also occurs during a short-term (1 week) oral gluten challenge, and that hookworm infection suppressed the increase of circulating CD4+CD25+Foxp3+ cells during this challenge period." (PMID 21949691, 2011). "Ascaris lumbricoides, Schistosoma mansoni, and hookworm infection in healthy controls contributed equally to decreasing the frequency of IFN-γ+CD4+ T cells, whereas in both LTBI and PTB patients S. mansoni coinfection had the greatest impact on reducing IFN-γ producing capacity of T cells." (PMID 36662839, 2023). "The possible explanation might be a presence of a low number of activated CD4+ and CD8+ T cells and an increased number of exhausted CD4+ T cells during hookworm infection in TB." (PMID 35976976, 2022). "After hookworm infection, CD4+T cells and ILC2s cooperate to quickly expel worms within 48 hours." (PMID 35592688, 2022). "Thus, hookworm infection is associated with alterations in homeostatic levels of total CD8+ T cells, the relative frequencies of both CD4+ and CD8+ effector memory T cells as well as baseline frequency of DC subsets." (PMID 23056659, 2012). "Moreover, we also identified the presence of significantly lower frequencies of both CD4+ and CD8+ effector memory T cells in hookworm infections, although an association between MT with altered T cell memory needs to be demonstrated." (PMID 23056659, 2012). "In order to determine the possible effect of Treg cells on the immune response during hookworm infection, functional assays were designed to evaluate whether CD4+CD25+FOXP3+ Treg cells could modulate the in vitro cellular proliferation of CD4+ and CD8+ lymphocytes after parasite antigen stimulation." (PMID 22087344, 2011).
hookworm infection (continued). "To determine the association of MT with alterations in T cell subsets, we measured the frequencies of different CD4+ and CD8+ T cell subsets in hookworm infection." (PMID 23056659, 2012). "Further, A. lumbricoides showed a non-significant reducing trend of IFN-γ+CD4+ T cells while hookworm infection had little effect." (PMID 36662839, 2023). "The CD4+ IELcounts were not significantly affected by either in vivowheat challenge or hookworm infection." (PMID 21408161, 2011). "Unfortunately functional assays of CD4+Foxp3+ suppression were not within the scope of this study, so we cannot say whether the hookworm infection increased suppressive ability and so suppressed inflammatory cytokine production." (PMID 21949691, 2011). "Also, expression of CTLA-4 on these CD4+/CD25+ T-cells was not analysed and further experiments are needed to elucidate the role of this cell population during hookworm infection." (PMID 17576364, 2007).
ileitis (14 papers, 2012 to 2025). "For example, gene networks associated with ileitis were suppressed ~8% (P < 0.05), and included Cd36, Il4, Cd44, Cd4, and Cd40." (PMID 28446880, 2017). "Previous study demonstrated that severe ileitis was correlated with decreased number of regulatory CD4 T cells in the lamina propria and mesenteric lymph nodes." (PMID 28812128, 2017). "In all, these results indicate that the MLNs in TNFi∆ARE/i∆ARE mice are populated with effector CD4+ lymphocytes that possess the ability to induce ileitis upon adoptive transfer to immunologically naïve mice." (PMID 23977323, 2013). "On the other hand, TH2 cells may directly cause intestinal inflammation, as seen by experiments in which IL-4 expressing CD4+ T cells from mice with ileitis were sufficient to initiate ileitis upon being adoptively transferred in immunocompromised recipients." (PMID 34581755, 2021). "During T. gondii infection, the accompanying dysbiosis and bacterial translocation contributes to the development of lethal ileitis mediated by CD4+ T cells, but whether CD4+ T cells directly impact dysbiosis is unclear." (PMID 31138751, 2019). "The accumulation of macrophages and CD4-positive T cells in the lamina propria of samples from T. gondii-induced ileitis is also compatible with the activation of innate and adaptive immune mechanisms, which are attenuated by concurrent infection with S. mansoni." (PMID 30936867, 2019). "Finally, we provide evidence that these activated lymphocytes display properties of CD4+ effector cells, as they are capable of inducing ileitis in immunologically naïve recipients via the generation of a mixed Th1/Th2 cytokine response." (PMID 23977323, 2013). "Intestinal inflammation in TNFi∆ARE/i∆ARE mice was mediated through the generation of effector CD4+ lymphocytes, which expressed markers of activation, adoptively transferred ileitis to immunologically naïve recipients, and secreted pro-inflammatory cytokines of both Th1 and Th2 immunophenotypes." (PMID 23977323, 2013). "T. gondii is known to induce ileitis with CD-like immunopathology in C57BL/6 mice, i.e. CD4+ T-cell mediated inflammation dominated by Th1 cytokines TNF-α and IFN-γ." (PMID 22848538, 2012). "While the ability of CD4+ T cell-derived IFN-γ to stimulate macrophage production of iNOS is required for the control of T. gondii, previous studies have proposed that iNOS also participates in ileitis." (PMID 31138751, 2019). "In the lungs of SHIP-1−/− mice without ileitis there was an expansion of CD4+ and CD8+ T cells compared to controls, although this was not seen in SHIP-1−/− mice with ileitis." (PMID 39432107, 2024). "Our results clearly demonstrate the ability of CD4+ cells from TNFi∆ARE/i∆ARE mice, but not from wt mice, to induce severe ileitis when transferred to SCID recipients." (PMID 23977323, 2013).